SCNM1 (sodium channel modifier 1)
Description:
As a component of the minor spliceosome, involved in the splicing of U12-type introns in pre-mRNAs. Plays a role in the regulation of primary cilia length and Hedgehog signaling.
Synonyms: MGC3180; TNFAIP8L2-SCNM1; OFD19
Tractability: Small molecule: a structure with a bound ligand is known. PROTAC: UniProt records ubiquitination sites on it; ubiquitination databases record sites on it.
Gene: Protein-coding gene on chromosome 1 (151,156,664 to 151,170,296, forward strand). Ensembl gene ENSG00000163156.
Subcellular location: Nucleus, nucleoplasm; Nucleus speckle
Subcellular location (Human Protein Atlas): Nucleoplasm
Gene Ontology:
Molecular function: enzyme binding; protein binding
Biological process: alternative mRNA splicing, via spliceosome; mRNA splicing, via spliceosome; RNA splicing; spliceosome conformational change to release U4 (or U4atac) and U1 (or U11)
Cellular component: nuclear speck; spliceosomal complex; U12-type catalytic step 2 spliceosome; U12-type precatalytic spliceosome; U12-type spliceosomal complex; nucleus; nucleoplasm
Genetic constraint (gnomAD): Loss-of-function variants: 24 observed, 34.03 expected, observed/expected ratio (o/e) 0.71, 90% interval 0.51 to 0.99. The upper end of that interval is the gene's LOEUF score, 0.99, which puts it in group 4 of 6, group 1 being the genes least tolerant of losing a copy. Missense variants: 274 observed, 296.38 expected, observed/expected ratio (o/e) 0.92, 90% interval 0.84 to 1.02. Synonymous variants: 99 observed, 109.29 expected, observed/expected ratio (o/e) 0.91, 90% interval 0.77 to 1.07.
Homologues: Orthologues: chimpanzee SCNM1 (99% identical), macaque SCNM1 (98% identical), rabbit SCNM1 (91% identical), pig SCNM1 (89% identical), dog SCNM1 (87% identical), guinea pig SCNM1 (85% identical), rat Scnm1 (82% identical), mouse Scnm1 (64% identical), tropical clawed frog scnm1 (51% identical), zebrafish scnm1 (47% identical).
Diseases named in the same sentence as SCNM1 in open-access papers:
SCNM1 is named in the same sentence as 2 diseases in open-access papers, as found by Europe PMC text mining. Sharing a sentence is not in itself a finding about the gene and the disease.
SCNM1 shares sentences with these, for which no sentence is quoted: epilepsy (1 paper); movement disorder (1).